HGF (hepatocyte growth factor)
Diseases named in the same sentence as HGF in open-access papers (continued):
Sharing a sentence is not in itself a finding about the gene and the disease.
melanoma (continued). "In melanoma, foretinib inhibited HGF-induced cell migration and invasion, MET phosphorylation, tumor growth and lung metastases of B16F10 model." (PMID 33918490, 2021). "In a melanoma mouse model, the hepatocyte growth factor (HGF) and TGF-β1 secreted by PMN-MDSC have been revealed to play a considerable role in inducing EMT in cancer cells of primary site." (PMID 34689842, 2021). "Qin and colleagues, by using melanoma 3D spheroids and 2D hypoxic cultures, demonstrated that hypoxia-driven upregulation of hepatocyte growth factor (HGF)/MET pathway plays an important role in vemurafenib resistance." (PMID 33964953, 2021). "We confirmed some well-known biomarkers already reported in melanoma progression, such as organ-specific alterations of historical metastasis genes and HGF-MET autocrine reactivation." (PMID 34885093, 2021). "Stromal HGF’s role in the induction of therapy resistance in melanoma was also confirmed by the work of Wilson’s group." (PMID 34067929, 2021). "Beyond expectation, this combo not only promoted the T cell activation and proliferation to a much higher level compared to single HGF made but impeded the hypermetastatic performance of metastatic B16F10 melanoma in the whole-body system." (PMID 34593794, 2021). "Herein, we selectively ablated the tandemly arranged Nme1 and Nme2 genes to assess their individual impacts on metastatic activity in a mouse model (HGF:p16−/−) of ultraviolet radiation (UVR)-induced melanoma." (PMID 33024267, 2021). "Overexpression of another tyrosine kinase receptor c-MET and its ligand HGF (hepatocyte growth factor) correlates with melanoma progression." (PMID 34203771, 2021). "Dissimilar to melanocytes, melanoma cells not only express c-met, but also release HGF, thus generating an autocrine loop." (PMID 33451139, 2021). "It is widely described that HGF confers resistance to the BRAF inhibitor Vemurafenib in BRAF-mutant melanoma cells." (PMID 33003469, 2020). "Most importantly, the authors confirmed increased HGF expression in stromal cells of BRAF-mutant melanoma patients undergoing BRAF-targeted treatment in vivo, which resulted in poor prognosis and decreased response to treatments." (PMID 33036192, 2020). "IPA found indirect inhibition of DSG1 by HGF in malignant melanoma highlighting that DSG1 down-regulation contributes to cell-cell adhesion disruption easing invasion." (PMID 32564264, 2020). "HGF can bind RTK on the surface of melanoma cells, which increases intracellular signaling, which promotes RAS expression, finally leading to the activation of the MAPK signal transduction pathway." (PMID 32605090, 2020). "Treatment of melanoma cell lines with hepatocyte growth factor (HGF), the ligand for the c-MET receptor, led to increased levels of phosphorylated STAT3 in two of three parental lines tested (MM455 and MM603)." (PMID 32632141, 2020). "While MET receptors, also known as HGF receptors, are mainly expressed in epithelial cells of many tissues, including the skin, oncogenic effects of the HGF/MET signaling pathway has long been observed in melanoma and other malignancies." (PMID 33031392, 2020). "Upregulation of MET expression on tumor cells leads to an exacerbated HGF signaling and allows HGF to protect melanoma cells from apoptosis, highlighting a feed forward loop between HGF and cMET to favor treatment resistance." (PMID 33276788, 2020). "Primary resistance to BRAF is induced due to HGF secretion by stroma cells (i.e., fibroblasts) within the tumor and its paracrine signaling to melanoma cells." (PMID 32605090, 2020). "Mechanistically, GD3 has been shown to mediate melanoma cell proliferation through the convergence of pro-tumoral signals such as hepatocyte growth factor (HGF) and the c-MET receptor tyrosine kinase." (PMID 33121001, 2020). "Throughout all experiments, cells were treated with 5 nM EGF and 30 ng/ml HGF to mimic conditions present in the melanoma microenvironment." (PMID 31649529, 2019).
melanoma (continued). "While treatment with BRAF- and MEK-inhibitors is not sufficient to overcome HGF-induced resistance, BRAF- and MET (the HGF receptor)-inhibitors suppress the majority of HGF-induced drug resistance in BRAF-mutant melanoma." (PMID 31067787, 2019). "The gene that encodes the HGF interactor SRPX2 proved to be subjected to a high intensity phenomenon of intron retention, specifically in melanoma samples." (PMID 30795533, 2019). "We previously showed that EGF and HGF stimulate invadopodia formation and extracellular matrix degradation, which correlates with higher invasive abilities of melanoma cells." (PMID 31649529, 2019). "In relevance, the GHRKO and the Ames’ mice have lower α-MSH immunoreactivity in the hypothalamus; while a GH-regulated HGF-MET expression was observed in human melanoma cells." (PMID 31547367, 2019). "Another melanoma mouse model, constitutively expressing hepatocyte growth factor/scatter factor (HGF/SF) for the migration of melanocytes to the epidermis, develops melanoma at the dermo-epidermal junction upon ultraviolet (UV) irradiation." (PMID 31685822, 2019). "Quercetin attenuated tumor proliferation, invasion, and migration through inhibiting hepatocyte growth factor (HGF)/c-Met signaling in melanoma cells." (PMID 31064104, 2019). "For instance, in melanoma patients, increased secretion of HGF from surrounding stromal cells increases MET pathway signaling in melanoma cells, resulting in resilience against BRAF targeted inhibitors." (PMID 31815659, 2019). "Several reports have indicated that the overexpression and hyper-activation of c-Met (receptor tyrosine kinase) when it binds to its ligand hepatocyte growth factor (HGF), play an important role in melanoma development." (PMID 31126298, 2019). "Already in the early 1990s, HGF has been shown to contribute to melanoma growth, and c-MET has been detected on melanoma cells." (PMID 30513872, 2018). "Apoptosis induced by the knockdown of BRAFV600E in melanoma cells can be prevented by growth factors, including HGF." (PMID 30513872, 2018). "Next, melanoma cells were exposed to either PLX-4720 or PD-184352 (MEK1/2 inhibitor) in the presence of increasing concentrations (6.25–50 ng/mL) of recombinant HGF, HGF-neutralizing antibodies, or crizotinib, a MET inhibitor." (PMID 30513872, 2018). "We summarize recent studies, which involved inhibition of the HGF/c-Met signaling in order to decrease melanoma growth and metastatic capacity." (PMID 29455657, 2018). "NRAS-mutated melanoma cell lines (SB2 and SK-Mel-2) migrate efficiently toward HGF but this process is completely inhibited by PHA-665752, and treatment with 50–100 nM PHA-665752 inhibited phosphorylation of Akt." (PMID 29455657, 2018). "The role of HGF/c-MET signaling in response of melanoma to targeted therapies, and subsequent development of resistance has been investigated, which has resulted in several publications." (PMID 30513872, 2018). "The involvement of the HGF/c-Met signaling in solid tumors, including melanoma, prompted development of new drugs, which have already brought benefit in clinical setting." (PMID 29455657, 2018). "Stimulation of the HGF/c-MET pathways contributes to several processes that are crucial for melanoma development, such as proliferation, survival, motility, and invasiveness, including distant metastatic niche formation." (PMID 30513872, 2018). "Among 12 additional BRAFV600E melanoma cell lines, HGF markedly antagonized vemurafenib sensitivity only in five lines." (PMID 30513872, 2018). "Autocrine expression and the activation of HGF downregulates the expression of E-cadherin and Desmoglein 1, which decouples melanoma cells from keratinocytes." (PMID 30513872, 2018). "Other factors, such as adenosine and vascular endothelial growth factor (VEGF), also increase the proliferation of DPC or hair growth by activation of ERK, whereas hepatocyte growth factor (HGF) induces the proliferation of melanoma cells by activation of p38." (PMID 30223485, 2018).
melanoma (continued). "It has been recently shown that HGF can contribute to the induction of the invadopodia formation, which was correlated with an enhanced invasive potential of melanoma cells." (PMID 30513872, 2018). "HGF/c-MET signaling promotes the metastatic dissemination of melanoma cells, also through exosomes that are used for intercellular communication." (PMID 30513872, 2018). "The mechanism of HGF/c-MET signaling contribution to melanoma cell protection from apoptosis is, to some extent, similar as in melanocytes." (PMID 30513872, 2018). "HGF has been recognized as contributing to the regulation of the interaction between melanoma cells and their microenvironment." (PMID 30513872, 2018). "It has been demonstrated in preclinical studies that the enhanced activity of HGF/c-MET can activate the proliferation of melanoma cells, increase their invasive capacity, and protect melanoma cells from apoptosis." (PMID 30513872, 2018). "It has been earlier shown that melanoma patients with a high stromal HGF level had a poorer response to treatment with vemurafenib, an inhibitor of BRAFV600E, used alone or in combination with trametinib, an inhibitor of MEK1/2, than those lacking HGF." (PMID 30513872, 2018). "The proliferation of melanoma cells was less inhibited by PLX-4720 in the medium from HGF-secreting fibroblast cultures than in the fresh medium." (PMID 30513872, 2018). "Activation of p38 has a negative effect such as mitotic arrest and cyclin D1 reduction in cell proliferation, while p38 inhibitors inhibited melanoma cell proliferation by HGF in another report." (PMID 30223485, 2018). "This review focuses on the role of HGF/c-MET signaling in melanoma with some introductory information on its function in skin and melanocytes." (PMID 30513872, 2018). "Elevated HGF levels in blood as well as presence of Met-containing exosomes are connected to melanoma metastases and resistance to therapy." (PMID 29236046, 2017). "A marked influence of recombinant HGF (0.25–50 ng/ml) on the vemurafenib analog (PLX4720)-inhibited proliferation was observed only in one (SK-MEL-5) out of 3 melanoma cell lines." (PMID 28829835, 2017). "In this study, we highlight the ability of HGF to rescue BRAFV600E mutant melanoma cell lines from the effects of BRAF and/or MEK inhibition, observing evidence of HGF rescue in the majority of profiled cell lines." (PMID 28147313, 2017). "Having observed significant HGF rescue in the initial panel of cell lines, an additional 12 patient-derived BRAFV600E mutant melanoma cell lines with accompanying clinical data were profiled for HGF rescue." (PMID 28147313, 2017). "HGF was the predominant growth factor capable of rescuing BRAFV600E mutant melanoma cell lines from vemurafenib." (PMID 28147313, 2017). "Among 12 additional V600EBRAF melanoma cell lines, HGF significantly attenuated vemurafenib sensitivity only in 5 lines." (PMID 28829835, 2017). "Introduction of the p16INK4AP16INK4A-null genotype into HGF/SF mice was shown previously to cut melanoma onset time by more than half, from 6–12 months to 2–3 months." (PMID 28788083, 2017). "UV-induced melanomas in the HGF/SF model are composed of heavily pigmented epithelioid and dendritic melanocytes with high proliferative potential." (PMID 28788083, 2017). "RT-qPCR analysis of 17 human melanoma samples have identified and subsequent experiments have confirmed the existence of a tumor driving HGF-MET axis." (PMID 28223541, 2017). "Similar to IL-8, production of HGF by stromal cells and activation of Met receptor by HGF, influences melanoma invasiveness." (PMID 29236046, 2017). "In a later study, however, liver metastasis was indeed observed in UVB-induced melanomas with the CDK4R24C × HGF/SF model." (PMID 28788083, 2017). "Profiling BRAFV600E mutant melanoma cell lines identified considerable diversity in the degree of HGF rescue from vemurafenib." (PMID 28147313, 2017).
melanoma (continued). "Initial reports documenting HGF-mediated resistance to BRAF inhibition in BRAF mutant melanoma identified correlations between HGF expression levels and patient response to BRAF and/or MEK inhibitor therapy." (PMID 28147313, 2017). "Downstream increases in ERK and AKT phosphorylation were also observed, suggesting that changes in total MET and GAB1 prime BRAF mutant melanoma cells for HGF-mediated rescue via downstream activation of the PI3K and MAPK signaling pathways." (PMID 28147313, 2017). "This review is focused specifically on the hepatocyte growth factor/scatter factor (HGF/SF) mouse model of UV-induced melanoma as a means for measuring metastasis-regulating activity of genes in vivo." (PMID 28788083, 2017). "Overall, however, multiple studies have provided valuable proof-of-principle for the HGF/SF model of UV-induced melanoma as a sensor of MSG activity." (PMID 28788083, 2017). "HGF-expressing stromal cells appeared following treatment with BRAFV600E inhibitors in a melanoma patient." (PMID 28708099, 2017). "A primary attribute of the HGF/SF model is the UV-initiated character of its melanomas, which recapitulates the UV-dependence of most human melanomas." (PMID 28788083, 2017). "The level of HGF was a few hundred-fold higher in the medium when exogenous HGF (40 ng/ml) was added in comparison to the medium with HGF released exclusively by melanoma cells." (PMID 28829835, 2017). "Our in vitro drug studies confirmed that high level of HGF/MET signaling correlates with low sensitivity to a BRAF(V600E) inhibitor in melanoma." (PMID 28453553, 2017). "We also noted that the absence of Mcpt4/Mcpt6/CPA3 was associated with alterations in the expression a range of other genes of potential impact on the melanoma colonization processes: HGF, MMP2, FGF, CXCL2." (PMID 28212574, 2017). "The MET-deregulated hepatocyte growth factor/scatter factor (HGF/SF)-transgenic mouse model develops UV-dependent tumors that resemble human melanomas with respect to histopathology, etiology and molecular wiring." (PMID 27846237, 2016). "SPINT2: The epigenetic silencing of SPINT2 promoted cancer cell motility via HGF-MET pathway activation in melanoma, and β-catenin formed a complex with c-Met (HGF receptor)." (PMID 27534621, 2016). "We have discovered that UV-initiated melanomas driven by the HGF/SF-transgene arise with a significantly higher frequency and shorter latency when deficient in ARF relative to INK4a." (PMID 27846237, 2016). "This is of particular interest since several of the currently proposed drug resistance mechanisms against melanoma, through upregulation of C-Raf, B-Raf, hepatocyte growth factor or PDGFR, reactivate the signaling pathways which are mediated by SHP2." (PMID 27650545, 2016). "Our findings suggest that suppression of the HGF/c-Met signaling pathway contributes to the anti-metastatic action of quercetin in melanoma." (PMID 25971889, 2015). "The effects of quercetin on HGF-stimulated melanoma cell migration and invasion were determined by the Transwell chamber assays." (PMID 25971889, 2015). "It is reported that most of melanoma cells produce HGF that induces sustained activation of its receptor c-Met." (PMID 25971889, 2015). "The first evidence for stroma-mediated drug resistance in melanoma came from studies demonstrating the role of stroma-derived hepatocyte growth factor (HGF) in BRAF inhibitor resistance." (PMID 26622938, 2015). "Plexin B1 has been shown to inhibit c-Met in response to its ligand hepatocyte growth factor (HGF) and is predicted to be a classic tumor suppressor protein in melanomas in which progression is c-Met dependent." (PMID 26052356, 2015). "Real-time PCR data showed that the mRNA expression levels of HGF in melanoma A375 and A2058 cells were slightly reduced after treating with quercetin for 24 h." (PMID 25971889, 2015).
melanoma (continued). "In parallel, a Matrigel invasion assay showed that stimulation with HGF significantly increased the invasiveness of melanoma cells at both 24 h- and 48 h-incubation periods, and this effect was dose-dependently reverted by quercetin treatments." (PMID 25971889, 2015). "Since some melanoma cells were reported to express HGF and secret a detectable level of HGF to induce constitutive activation of c-Met, we wondered if quercetin exerted its effects by affecting HGF autocrine." (PMID 25971889, 2015). "In this study, we sought to determine the involvement of HGF/c-Met signaling in the anti-metastatic action of quercetin in melanoma." (PMID 25971889, 2015). "Quercetin also inhibited HGF-stimulated melanoma cell migration and invasion, which was in agreement with the previous studies that quercetin inhibited HGF-stimulated migration and invasion in human medulloblastoma cell DAOY and human hepatoma HepG2 cells." (PMID 25971889, 2015). "Our work demonstrates that fibronectin secreted in response to vemurafenib treatment can augment RTK signaling in melanoma cells, allowing them to take full advantage of the growth factors (HGF and NRG-1) secreted from fibroblasts." (PMID 26622938, 2015). "Damm suggested that HGF stimulates the secretion of CD44 by melanoma cells by activating the nuclear factor-κB signaling pathway." (PMID 25658794, 2015). "Hepatocyte growth factor (HGF)-mediated activation of c-Met signaling has been suggested as a therapeutic target for melanoma metastasis." (PMID 25971889, 2015). "HGF/c-MET binding up-regulates the expression of CD44v6 in murine melanoma cells through transcriptional activation of the immediate early gene egr-1; HGF seems to induce egr-1 activation via the Ras-Erk1/2 pathway." (PMID 28536400, 2015). "An important study demonstrated production of HGF by stromal cells in patients with melanoma, which resulted in activation of the HGF receptor MET, reactivation of the MAPK and PI3K pathways, and resistance to BRAF." (PMID 24743024, 2014). "Melanoma cells harvested directly from an HGF-transgenic/CDKN2A-knockout FVB/N mouse were transduced with the ffLuc-eGFP gene ex vivo, and transplanted subcutaneously into syngeneic FVB/N mice." (PMID 25369133, 2014). "In transgenic mice over-expressing NK2, NK2 inhibited HGF-induced melanoma cell proliferation in vivo." (PMID 28548073, 2014). "Caenepeel and colleagues reported that HGF rescued melanoma cell lines,notably SK-MEL-5, from BRAF or MEK inhibition using vemurafenib (an analogue of PLX4720)or PD0325901, respectively, and the rescue was attenuated by MET inhibition." (PMID 25490933, 2014). "Metastasis-prone melanomas of the HGF+ × [m1m2]+/− strain are likely to have acquired metastasis-driving mutations, and loss of the genomic stabilizing activity of NM23 is a plausible candidate mechanism." (PMID 22699362, 2013). "The HGF+ strain exhibits a form of UVR-induced melanoma with human characteristics, rapid growth but minimal metastatic potential." (PMID 22699362, 2013). "All three HGF+-derived cell lines consisted of cells that displayed minimal migration with short trajectories, in contrast to cells isolated from HGF+ × [m1m2]+/− melanomas that exhibited highly motile behavior and much longer trajectories." (PMID 22699362, 2013). "To assess the role of NM23-M1 and NM23-M2 in melanoma progression in vivo, we have crossed [m1m2]+/− mice with a transgenic mouse strain engineered for overexpression of hepatocyte growth factor (HGF+)." (PMID 22699362, 2013). "However, the robust nature of UVR-induced melanomas obtained in the HGF+ model strongly suggests tumor-driving mutations are readily acquired independent of NM23 status, which may have obscured the effects of nm23-m1/m2 deficiency on tumor initiation and growth." (PMID 22699362, 2013).